CYFIP2 (cytoplasmic FMR1 interacting protein 2)
Diseases named in the same sentence as CYFIP2 in open-access papers (continued):
Sharing a sentence is not in itself a finding about the gene and the disease.
cancer (continued). "Similar to CYFIP2, whether its expression is favourable or adverse appears to be cancer-dependent, but the majority of research suggests that high expression is associated with unfavourable clinical outcomes." (PMID 38473425, 2024). "Our study demonstrated that CYFIP2 was aberrantly expressed in different cancers." (PMID 37735711, 2023). "However, the comprehensive function and prognostic landscape of CYFIP2 involved in human cancers are still not fully understood." (PMID 37735711, 2023). "Besides, the specific mechanisms of CYFIP2 involved in cancer initiation and progression remain to be unclear." (PMID 37735711, 2023). "CYFIP2 may also interact closely with some genes in the initiation and progression of different cancers." (PMID 37735711, 2023). "Notably, the expression and potential role of NUDT7, NUDT11, and CYFIP2 in cancer are becoming increasingly important." (PMID 35614925, 2022). "In addition, pan–cancer–based immune cell infiltration analysis also revealed that CYFIP2 is closely related to T–cell CD8+, T–cell CD4+ and neutrophils." (PMID 35898498, 2022). "For further pan–cancer analysis, CYFIP2 was considered the most potential target both in RA and 33 kinds of tumors, which may shed the hoping light on the therapy of human immune–related diseases and even cancer." (PMID 35898498, 2022). "However, whether CYFIP2 expression is favourable or adverse appears to be dependent on the specific type of cancer." (PMID 38473425, 2024). "Therefore, we further explored the role of the hub gene found in RA, CYFIP2, in pan–cancer." (PMID 35898498, 2022). "To facilitate the clinical transformation of the five genes model, we further identified FDA-approved sensitive drugs that express high levels of CYFIP2, EIF4A1, NUDT1, NUDT4, and NUDT10 in multiple cancer cell types." (PMID 37089261, 2023). "The results revealed that CYFIP2 expression was positively correlated with B cells, CD8 + T cells, CD4 + T cells, macrophages, neutrophils, and dendritic cells in most cancer types based on all or most algorithms, especially in LUAD." (PMID 37735711, 2023). "In addition, CYFIP2 expression was also highly related to almost most chemokines, chemokine receptors, and MHC genes in different cancers." (PMID 37735711, 2023). "However, the expression of CYFIP2, IFIT5, and NUDT4 were negatively correlated with the prognosis of most cancer patients." (PMID 36226166, 2022). "In addition, despite the finding indicating that CYFIP2 expression correlated with both immune cell infiltration and patient survival in cancers, we could not prove that CYFIP2 affects patient survival through immune infiltration." (PMID 37735711, 2023).
infection (6 papers, 2018 to 2023). The state of being infected such as from the introduction of a foreign agent such as serum, vaccine, antigenic substance or organism. "In addition, CCR5-deficiency during infection affected the upregulation of cytokine genes such as Csf2, Csf3, Cxcl1, Edn1, and Il6 and other genes associated with immune response (i.e., Gimap6, Mcoln2) and migration (i.e., Cyfip2)." (PMID 31506064, 2019). "We identified 11 genes that were significantly altered after infection with both viruses, and among these genes, 6 were up-regulated after infection (Chl1, Nlrp12, Plk1, Cyfip2, Adamts3, and Pdzk1)." (PMID 30713529, 2018).
neurodevelopmental disorder (6 papers, 2019 to 2026). A behavioral and cognitive disorder with onset during the developmental period that involves impaired or aberrant development of intellectual, motor, or social functions. "This study extends the functional scope of CYFIP2 to the PNS and establishes the diaphragm as a tractable model for investigating peripheral mechanisms underlying CYFIP2-associated neurodevelopmental disorders." (PMID 42035098, 2026). "Supporting its critical roles in proper neuronal development and function, human genetic studies have repeatedly identified variants of the CYFIP2 gene in individuals diagnosed with neurodevelopmental disorders." (PMID 36999135, 2023). "Other studies found mutations in CYFIP2, again causative for neurodevelopmental disorders, which were accused of causing gain-of-function with respect to WRC activation, but experimental evidence for this assumption was hitherto missing." (PMID 32486060, 2020). "Many missense mutations that cause the neurodevelopmental disorder DEE-65 are clustered around the A site and the tyrosine lock region, which was previously named the “Cyfip2 hotspot #1”19." (PMID 36114192, 2022).
brain disorder (5 papers, 2018 to 2025). A disease affecting the brain or part of the brain. "Recent molecular genetic studies have suggested that two members of the cytoplasmic FMR1-interacting protein (CYFIP) gene family, CYFIP1 and CYFIP2, are causally associated with several brain disorders." (PMID 31853374, 2019). "More importantly, genetic variants of CYFIP1 and CYFIP2 are associated with different types of brain disorders." (PMID 31853374, 2019). "Both CYFIP1 and CYFIP2 genes are associated with various brain disorders." (PMID 33192297, 2020). "Whether WAVE2, NCKAP1L and CYFIP2 function in T cells; WAVE1 and WAVE2 function in macrophages; or WAVE complex-mediated actin polymerization in peripheral and central immune cells is involved in pathogenic or protective mechanisms for brain disorders remains to be explored." (PMID 39774290, 2025). "However, the detailed mechanisms underlying the in vivo differences between CYFIP1 and CYFIP2 remain largely unexplored, which is an important issue toward understanding the pathophysiology of and potential treatments for various CYFIP-associated brain disorders." (PMID 31853374, 2019).
neurological disorders (3 papers, 2019 to 2024). "Our data suggest that increased CYFIP2 dosage could lead to altered synaptic inhibition, which may contribute to the pathology underlying CYFIP2-associated neurological disorders." (PMID 30784587, 2019). "In mice (Mus musculus), mutations in the CYFIP2 and SGSM1 genes can influence many neurological disorders." (PMID 39829673, 2024).
psychiatric disorder (3 papers, 2014 to 2023). A disorder characterized by behavioral and/or psychological abnormalities, often accompanied by physical symptoms. "This suggests that it will be interesting to further explore whether CYFIP2 is a candidate susceptibility gene for major mental illness." (PMID 24667445, 2014). "However, the function of CYFIP2 in psychiatric disorders is not clear." (PMID 37033658, 2023).
digestive system cancer (1 paper, 2022). A primary or metastatic malignant neoplasm involving any part of the digestive system. "From the overall situation of the current research, CYFIP2 has been studied more in digestive system cancers." (PMID 35898498, 2022).
CYFIP2 also shares sentences with these, for which no sentence is quoted: clear cell renal cell carcinoma (3 papers); early-onset epileptic encephalopathy (3); breast carcinoma (2); primary immunodeficiency (2); Allergy (1); astrocytoma (1); autosomal dominant intellectual disability (1); Baraitser-Winter syndrome (1); bladder cancer (1); Cocaine addiction (1); Cognitive impairment (1); colon adenocarcinoma (1); colorectal adenocarcinoma (1); colorectal tumors (1); dementia (1); developmental and epileptic encephalopathy (1); ectodermal dysplasia (1); enteritis (1); hypopharyngeal carcinoma (1); infantile epileptic encephalopathy (1); influenza (1); liver cancer (1); lung carcinoma (1); metabolic disorder (1); osteoporosis (1); pancreatic cancer (1); rheumatoid arthritis (1); Salmonella Infections (1); sarcopenia (1); T-cell lymphoma (1).
A further 3 diseases each share a sentence with CYFIP2 in 1 paper.